DNAJC30 (DnaJ heat shock protein family (Hsp40) member C30)
Description:
Mitochondrial protein enriched in neurons that acts as a regulator of mitochondrial respiration (By similarity). Associates with the ATP synthase complex and facilitates ATP synthesis (By similarity). May be a chaperone protein involved in the turnover of the subunits of mitochondrial complex I N-module. It facilitates the degradation of N-module subunits damaged by oxidative stress, and contributes to complex I functional efficiency.
Synonyms: WBSCR18; LHONAR; LHONAR1; MC1DN38
Tractability: Antibody: UniProt predicts a signal peptide or a membrane-spanning region. PROTAC: its protein half-life has been measured.
Gene: Protein-coding gene on chromosome 7 (73,680,918 to 73,683,453, reverse strand). Ensembl gene ENSG00000176410.
Subcellular location: Mitochondrion inner membrane
Gene Ontology:
Molecular function: protein binding
Biological process: brain development; regulation of mitochondrial ATP synthesis coupled proton transport
Cellular component: mitochondrial inner membrane; mitochondrion
Genetic constraint (gnomAD): Loss-of-function variants: 18 observed, 17.96 expected, observed/expected ratio (o/e) 1, 90% interval 0.69 to 1.48. The upper end of that interval is the gene's LOEUF score, 1.48, which puts it in group 6 of 6, group 1 being the genes least tolerant of losing a copy. Missense variants: 352 observed, 341.81 expected, observed/expected ratio (o/e) 1.03, 90% interval 0.94 to 1.12. Synonymous variants: 161 observed, 147.92 expected, observed/expected ratio (o/e) 1.09, 90% interval 0.96 to 1.24.
Gene-disease validity (ClinGen):
ClinGen rates the evidence that DNAJC30 causes each of these diseases.
Leber-like hereditary optic neuropathy, autosomal recessive 1 (autosomal recessive): Definitive.
Homologues: Orthologues: chimpanzee DNAJC30 (99% identical), macaque DNAJC30 (92% identical), pig DNAJC30 (75% identical), dog DNAJC30 (74% identical), rabbit DNAJC30 (74% identical), rat Dnajc30 (69% identical), mouse Dnajc30 (68% identical), guinea pig DNAJC30 (67% identical), tropical clawed frog dnajc30 (44% identical), zebrafish dnajc30b (34% identical), Drosophila melanogaster CG2790 (17% identical), Caenorhabditis elegans dnj-8 (17% identical), and 9 more. Paralogues in human: DNAJC16 (18% identical), DNAJC11 (18% identical), DNAJC13 (18% identical), DNAJC10 (17% identical), DNAJC21 (17% identical), DNAJC5 (17% identical), DNAJC7 (17% identical), DNAJC18 (16% identical), DNAJC1 (15% identical), DNAJC17 (15% identical), DNAJC2 (15% identical), DNAJC3 (15% identical), and 8 more.
Diseases named in the same sentence as DNAJC30 in open-access papers:
DNAJC30 is named in the same sentence as 10 diseases in open-access papers, as found by Europe PMC text mining. Sharing a sentence is not in itself a finding about the gene and the disease. The quoted sentences say what the papers report.
optic atrophy (4 papers, 2022 to 2025). A disorder characterized by loss of optic nerve fibers. "The reported yield of nuclear and mitochondrial DNA sequencing in bilateral optic atrophy is around 20% and includes pathogenic variants in the OPA1, mtDNA genes, or rarely WFS1, MFN2, POLG, ACO2, and DNAJC30 genes." (PMID 36294366, 2022).
Leigh syndrome (2 papers, 2023 to 2024). A progressive neurological disease defined by specific neuropathological features associating brainstem and basal ganglia lesions. "DNAJC30 mutations have been reported to affect complex I turn‐over and function and are associated also with Leigh syndrome." (PMID 38757769, 2024).
deafness (1 paper, 2021). An inherited or acquired condition characterized by the complete loss of the ability to hear from one or both ears. "These DNAJA3 anomalies are followed by early-onset deafness in ClpP-mutant patients, while a recent report showed anomalies of the mitochondrial matrix chaperone DNAJC30 to occur in hereditary optic nerve atrophy." (PMID 34345994, 2021).
cancer (2 papers, 2020 to 2021). A tumor composed of atypical neoplastic, often pleomorphic cells that invade other tissues. "Of interest, 16 (16/22, 72.7%) of them are HSP40 family members, including DNAJC28, which was associated with 10 hallmarks across 8 cancers; DNAJC19, which was associated with 8 hallmarks across 5 cancers; and DNAJC30, which was associated with 6 hallmarks across 5 cancers." (PMID 33225964, 2020).
DNAJC30 also shares sentences with these, for which no sentence is quoted: Optic neuropathy (3 papers); mitochondrial disease (2); Williams Beuren syndrome (2); diabetes (1); Parkinsonism (1); retinal degeneration (1).